DRD2 (dopamine receptor D2)
Diseases named in the same sentence as DRD2 in open-access papers (continued):
Sharing a sentence is not in itself a finding about the gene and the disease.
psychosis (continued). "The present study examined methylation rates of DRD2 and NR3C1 in patients with recent-onset (RO) psychosis using bisulfite pyrosequencing as well as its association with childhood trauma and rumination." (PMID 35968502, 2022). "We investigated methylation levels of DRD2 and NR3C1 in peripheral blood of patients with recent-onset (RO) psychosis using bisulfite pyrosequencing as well as its association with childhood trauma and rumination." (PMID 35968502, 2022). "Colizzi and colleagues (2015) investigated the dopamine receptor D2 (DRD2) genotype rs1076560 locus and found that cannabis-using carriers of the T-allele had a three-fold increase in the odds of psychosis compared to GG carriers (OR = 3.07; 95% CI 1.22–7.63)." (PMID 32059350, 2020). "The ZNF804A influences the expression of three genes involved directly in dopaminergic transmission (i.e. DRD2 and COMT) and cAMP signalling (i.e. PDE4B), two pathways thought to underlie many of the symptoms of psychosis." (PMID 28931092, 2017). "The present results suggest an interaction between DRD2 rs1076560 and AKT1 rs2494732 genotypes on psychosis risk among cannabis users." (PMID 27336035, 2015). "The analysis showed an increasing probability of suffering from a psychotic disorder in cannabis users depending on DRD2/AKT1 (N=450, likelihood ratio test=7.66; P=0.022)." (PMID 27336035, 2015). "A second multivariable logistic regression adjusting for the potential confounders showed a significant interaction between DRD2/AKT1 and lifetime frequency of cannabis use on risk of psychosis (N=402, likelihood ratio test =11.91; P=0.042)." (PMID 27336035, 2015). "1- Ziprasidone induced-supersensitivity psychosis by chronic blockade of DRD2 in mesolimbic brain." (PMID 34677234, 2021). "In the MTAG results, a total of 146 genes were observed for three or more disorders, including some genes that were previously known to be involved in psychosis, such as DRD2 and TCF4, which were originally reported in SCZ and DEP, while our data indicated their association with BD." (PMID 32606422, 2020). "The dopaminergic hypothesis is a longstanding SZ model, attributing positive symptoms of the disorder, in particular psychosis, to dysregulation in dopaminergic neurotransmission via the dopamine (DA) receptor D2 (DRD2)." (PMID 30546022, 2018). "It has been established that the blockade of DRD2 in post-synaptic neurons by antipsychotics plays an essential role in controlling psychosis, and presumed that the supersensitivity of the receptors caused by the antipsychotic blockade concurrently underlies the development of DSP." (PMID 26694375, 2015). "However, it is still necessary to block DRD2 when treating this disorder, since both first-episode and relapsed psychosis generally appears with positive symptoms in most patients, and physicians must address such situations with antipsychotics." (PMID 26694375, 2015). "In addition, DRD2 represents an interesting pharmacological target for the treatment of psychosis and ADORA2A has been suggested as a target for the treatment of psychiatric diseases." (PMID 25340473, 2014). "These associations between SNPs at DRD2 and cognition may be even more significant in those at risk for psychosis, though research in this area is lacking." (PMID 26114663, 2015). "One imaging study suggested differences in the correlation between dopamine receptor density and activation in the right middle frontal gyrus between those at clinical risk for psychosis and controls, but there has been no research on differences according to DRD2 SNPs." (PMID 26114663, 2015). "Indeed DRD2 is the target of the mesolimbic dopaminergic pathway projecting from the ventral tegmental area to the ventral striatum, whose dysfunction is regarded as the final common pathway for the positive symptoms of psychosis, both in the context of SCZ and BD." (PMID 37229261, 2023).
psychosis (continued). "We investigated DNA methylation rates at two candidate regions (DRD2 and NR3C1) in patients with RO psychosis and healthy controls." (PMID 35968502, 2022). "Pharmacological treatment of schizophrenia and psychosis includes the use of antipsychotics, which act as orthosteric receptor antagonists/partial agonists of various GPCR targets, including dopamine receptor D2 and serotonin receptor 5HT1A." (PMID 33036015, 2021). "Five genes, DRD2, DRD3, HTR2A, OPRD1 and HTR7, are found shared by psychosis network and antipsychotics network." (PMID 32273551, 2020). "A multivariable logistic regression adjusting for the modeled potential confounders showed a significant interaction between DRD2 rs1076560/AKT1 rs2494732 genotypes and lifetime cannabis use on probability of suffering from a psychotic disorder." (PMID 27336035, 2015). "We identified aberrant DNA methylation rates in patients with RO psychosis compared to healthy controls at several CpG sites of the NR3C1 exon 1F region but not at the target regions of DRD2." (PMID 35968502, 2022). "Interestingly, both dopamine receptor D2 and FAAH genotypes appear to modulate the effect of cannabis use on the development of psychosis, but these initial findings need to be replicated." (PMID 32059350, 2020). "We hypothesise that those at increased risk for psychosis should show stronger associations between DRD2 SNP variants associated with cognitive difficulties in other groups (C allele at rs6277 and T allele at rs1800497) and adverse cognitive outcomes than those not at risk for psychosis." (PMID 26114663, 2015). "Identification of the non-Drd-2 mechanism may help to identify novel non-Drd2 based therapeutic strategies for psychosis." (PMID 25122042, 2014). "Identification of the non-Drd-2 mechanism through which antipsychotics specifically modulate salience but not other behaviours may help to identify novel non-Drd-2 based therapeutic strategies for psychosis." (PMID 25122042, 2014). "SGAs are as clinically effective as FGAs for medical management of psychosis with lower incidences of EPS and hyperprolactinemia, likely because SGAs occupy less than 60% of striatal DRD2 (as opposed to FGAs, which can occupy 65%) and/or the faster dissociation from DRD2 binding sites." (PMID 40863247, 2025).
alcoholism (82 papers, 1995 to 2025). "The DRD2 A1 allele has been potentially linked to a subtype of alcoholism and reduced D2 receptor density in vitro." (PMID 41080838, 2025). "Numerous international studies have been performed since the initial association of the DRD2 Taq A1 allele with severe alcoholism in 1990." (PMID 38766604, 2024). "Specifically, DRD2 methylation was linked to scores on the AUDs Identification Test, Impaired Control Scale, and Alcohol Dependence Scale." (PMID 38766604, 2024). "We published our study in JAMA in 1990 linking the DRD2 Taq A1 allele to severe alcoholism, and there has been an explosion of genetic candidate association studies, including GWAS." (PMID 38765881, 2024). "Since its initial association with severe alcoholism in 1990, particularly through the identification of the DRD2 Taq A1 allele, numerous international investigations have been conducted to elucidate its role in different conditions." (PMID 38766604, 2024). "An association between severe alcoholism and the A1 allele of the DRD2 gene is strongly supported by this study of the largest sample of alcoholics to date." (PMID 38765881, 2024). "A review by Noble and Blum examined the association between the DRD2 locus Al allelic variation and alcoholism." (PMID 38765881, 2024). "This polymorphic pattern of the DRD2 gene suggested the presence of a susceptibility gene for at least one form of alcoholism on the q22-q23 region of chromosome 11." (PMID 38766604, 2024). "An allelic association between alcoholism and the DRD2 gene has been discovered in a blind experiment." (PMID 38765881, 2024). "It alters the availability of DRD2, and in the presence of the CC genotype has been associated with alcoholism." (PMID 38397159, 2024). "Accordingly, severe alcoholism can be caused by both alleles of the DRD2 gene at the 5’ and 3’ ends." (PMID 38765881, 2024). "This NIAAA editorial initiated the long-standing controversy over the role of the DRD2 Taq A1 allele and its putative association with alcoholism." (PMID 37560184, 2023). "Since 1990, when our laboratory published the association of the DRD2 Taq A1 allele and severe alcoholism in JAMA, there has been an explosion of genetic candidate association studies, including GWAS." (PMID 36143170, 2022). "Genetic studies have shown that people with TaqIA of the dopamine receptor D2 gene (DRD2A1) is significantly associated with alcohol dependence." (PMID 35757213, 2022). "Since 1990, when our laboratory published the association of the DRD2 Taq A1 allele and severe alcoholism in JAMA, there has been an explosion of genetic candidate association studies, including genome-wide association studies (GWAS)." (PMID 36579510, 2022). "The frequency of the TaqIA polymorphism of the dopamine receptor D2 gene associated with alcohol dependence was compared between the two OPAD groups." (PMID 35757213, 2022). "The first evidence for a genetic connection to alcoholism by Blum and Noble and associates involved the dopamine D2 receptor (DRD2) Taq 1 allele and severe alcoholism in 1990, boasting 24,890 articles listed in PUBMED (1/3/21)." (PMID 34770047, 2021). "Association of rs1076560 in DRD2, which were associated with low-stress resilience, previously was reported to influence memory, alcoholism and modulate the risk of opiate addiction and the dosage requirements of methadone substitution." (PMID 34492034, 2021). "This concept has resulted in a disputed study published in JAMA by Yale scientists concerning the role of DRD2 allele and alcoholism whereby controls came from a French cohort of Tourette’s syndrome." (PMID 34770047, 2021). "Large-scale meta-analysis has confirmed that DRD2 rs1800497 polymorphism was associated with alcohol dependence and even HIV positive alcohol abusers." (PMID 32764574, 2020). "An association of DRD2 Taq1A on alcohol consumption and presence of alcohol dependence has been previously reported in the literature." (PMID 33364985, 2020).
alcoholism (continued). "Data from in vivo and in vitro experiments show DRD2 to be a susceptibility gene for alcohol dependence, and altering DRD2 expression leads to differential responses to substances and stimuli, conferring increased risk for addiction." (PMID 31998841, 2020). "The − 141C Ins/Del polymorphism (SNP ID: rs6277), which is located on promoter of the DRD2 (gene map locus 11q23), alters striatal D2 receptor binding potentials, and is associated with alcoholism." (PMID 29234453, 2017). "The C957T polymorphism (SNP ID: rs1799732), which is located on exon 7 of the DRD2 (gene map locus 11q23), is known to alter DRD2 availability and be associated with alcoholism with higher prevalence of the CC genotype." (PMID 29234453, 2017). "DRD2 TaqI B is associated with alcoholism with conduct disorder in both white and Taiwanese subjects." (PMID 27580593, 2016). "In patients with a positive family history, haplotype I-C-A-A2 and Cloninger 1 alcoholics, haplotype I-T-A-A1 was less often present, confirming that haplotypes, which are supposed to induce a low DRD2 expression, were associated with alcohol dependence." (PMID 24878765, 2014). "Almost a decade before Carlsson and others were awarded the Nobel Prize the DA D2 receptor gene (DRD2) was first associated with severe alcoholism and is today the most widely studied gene in psychiatric genetics." (PMID 24878765, 2014). "Genetic association of dopamine D2 receptor (DRD2) gene with alcohol dependence is most widely studied." (PMID 24135011, 2013). "The DA D2 receptor gene (DRD2) first associated with severe alcoholism is the most widely studied gene in psychiatric genetics." (PMID 22408582, 2011). "Compared to the T– genotype (C/C), the T+ genotype (T/T, T/C) is associated with reduced translation of DRD2 mRNA and diminished DRD2 mRNA, leading to reduced DRD2 density and a predisposition to alcohol dependence." (PMID 22408582, 2011). "Presence of such clinical and genetic evidences has implicated DRD2 gene polymorphisms as strong candidates for alcoholism and therefore, they have been most widely studied." (PMID 20146828, 2010). "Possible association between polymorphisms at the DRD2 gene and alcohol dependence has been extensively investigated since first proposed in 1990." (PMID 20146828, 2010). "In a retrospective analysis, genetic association of three polymorphisms from DRD2 gene with alcohol dependence was investigated using a case-control approach." (PMID 20146828, 2010). "In view of the paucity of Indian data on genetic polymorphism of alcohol dependence, we aimed to investigate the association of DRD2 gene polymorphisms in alcohol dependent subjects of north Indian origin." (PMID 20146828, 2010). "The present study tested association of three polymorphisms -141C Ins/Del, TaqI B and TaqI A, present at DRD2 gene locus with alcohol dependence in north Indian subjects." (PMID 20146828, 2010). "Two polymorphisms namely, -141C Ins/Del and TaqI A in DRD2 seem to have clinical implications in the development of alcoholism." (PMID 20146828, 2010). "The DRD2 gene has three most commonly investigated polymorphisms (-141C Ins/Del, TaqI B and TaqI A) and the results are equivocal for their association with alcohol dependence." (PMID 20146828, 2010). "The study showed a significant association of -141C Ins allele and a trend of association of TaqI A1 allele of DRD2 with alcohol dependence." (PMID 20146828, 2010). "Previous genetic association studies of the dopamine receptors (D1-D5) and transporter protein (DAT) have indicated that DRD2 is involved in susceptibility to alcoholism." (PMID 20146828, 2010). "Mutations in two regions of the DRD2 gene (TaqI A and TaqI B), are associated with alcoholism and other drug use disorders." (PMID 20622998, 2010). "In particular, the DRD2 gene has been associated with alcohol dependence and, more broadly, with various forms of addiction." (PMID 23584813, 2008).
alcoholism (continued). "Male-limited associations of the DRD2 A1 allele with alcohol dependence and tobacco smoking have been reported previously." (PMID 17543096, 2007). "More than a decade ago, some studies implicated variations in the DRD2 gene as a factor influencing a person’s risk of developing severe alcoholism, although subsequent studies have provided mixed support for this claim." (PMID 12875048, 2002). "Accordingly, the COGA investigators also examined the association between the DRD2 gene and co-occurring alcohol dependence and habitual smoking." (PMID 15986718, 2000). "Genes involved in dopaminergic signal transmission in the brain were first implicated in alcoholism risk when researchers reported that a specific variant of the gene encoding the dopamine receptor DRD2 was associated with severe forms of alcoholism." (PMID 15706788, 1998). "Researchers have reported associations between DRD2 and alcoholism-related phenomena, including drug abuse and aberrations of brain electrical activity." (PMID 31798095, 1995). "The observed polymorphic pattern of the DRD2 gene and its variation in receptor expression strongly suggests the involvement of the dopaminergic system in predisposing individuals to at least one subtype of severe alcoholism." (PMID 38766604, 2024). "It has been found that the C957T polymorphism (SNP: rs1799732), located in exon 7 of DRD2 (gene map locus 11q23), alters the availability of DRD2 and that a higher frequency of the CC genotype is associated with a higher risk of alcoholism, nicotine dependence, and cannabis dependence." (PMID 38397159, 2024). "DRD2 gene allele 3’ Taq1 A1 has been associated with severe alcoholism in previous studies." (PMID 38765881, 2024). "Specifically, the Taq1A polymorphism of the dopamine D2 receptor (DRD2) gene has been comprehensively studied in relation to alcoholism, is over-represented in alcohol-de-pendent individuals, and is associated with a highly increased mortality rate in alcohol-dependent individuals." (PMID 39618491, 2024). "Moreover, since 1990, when our laboratory published the association of the DRD2 Taq A1 allele and severe alcoholism in JAMA, there has been an explosion of genetic candidate association studies, including GWAS." (PMID 37511777, 2023). "The first-ever confirmed candidate psychiatric genetic association study performed by Kenneth Blum and Ernest Noble and their team discovered a significant association between the minor DRD2 allele Taq A1 (rs 1800497 C>T) and severe alcoholism published in JAMA (1990)." (PMID 37560184, 2023). "The aim of this study was to assess the relationship between the severity of craving for alcohol and COMT polymorphisms DRD2 genes and traits of temperament and character, as well as selected clinical and anthropometric factors in patients with alcohol dependence." (PMID 34945190, 2021). "Since the 1990 finding of the association of the TaqA1 allele of the DRD2 gene and severe alcoholism, laboratories across the globe, including NIDA and NIAAA, have confirmed this early work and extended the importance of various candidate genes and even second messengers in the reward system." (PMID 33683627, 2021). "This genetic test, which combines addiction risk and P450 metabolic predilection (high or low metabolizes), may launch close to the 25th anniversary of the first association of the DRD2 gene with severe alcoholism." (PMID 28804788, 2017). "Thus, the mechanism underlying ALDH1A1-related alcoholism is different from the gene cluster of DRD2, DRD3, GRIN2B, and NTRK2, which is directly involved in behavioural rewarding effects of alcohol consumption." (PMID 28512340, 2017). "This was awarded on the basis of our earlier work showing anti-addiction activity of a nutraceutical consisting of amino-acid precursors and enkephalinase inhibition properties and our discovery of the first polymorphic gene (Dopamine D2 Receptor Gene [DRD2] to associate with severe alcoholism." (PMID 27617300, 2015).